ENSG00000212455
Synonyms: LOC124900534
Gene: Small nucleolar RNA gene on chromosome 2 (18,040,606 to 18,040,733, reverse strand). Ensembl gene ENSG00000212455.
Gene Ontology:
Biological process: RNA processing
Cellular component: nucleolus
Homologues: Paralogues in human: SNORA40 (91% identical), SNORA40B (91% identical), SNORA40C (88% identical).